EGFR (epidermal growth factor receptor)
Diseases named in the same sentence as EGFR in open-access papers (continued):
Sharing a sentence is not in itself a finding about the gene and the disease.
tumor (continued). "Specifically, EVs from drug-resistant tumor cells can horizontally transfer various components, such as drug-efflux pumps (e.g., ABCB1, ABCC1), miRNAs (e.g., miR-21-5p, miR-222), and regulatory proteins (e.g., TrpC5, EGFR), to drug-sensitive cells, thereby spreading a drug-resistant phenotype." (PMID 39403600, 2024). "In the IMpower010 trial, the difference in OS between atezolizumab and best supportive care (BSC) was more pronounced in patients without EGFR/ALK mutations and with PD-L1 tumor cells ≥ 50% (5-year OS 89.1% with atezolizumab and 77.5% with BSC [HR 0.42 (0.23–0.78)]." (PMID 39590145, 2024). "Among these, EGFR and MSLN seem to be the more promising targets compared to others: indeed, they showed higher antigen specificity and lower on-target, off-tumor toxicity concern, i.e., the potential healthy organ toxicity, due to the expression of these targets in tissues other than tumor." (PMID 39199653, 2024). "Interestingly, despite superior results in vitro, homodimeric EGFR T-BsAb treatment resulted in the poorest control of tumor growth and offered no significant benefit to survival." (PMID 38650005, 2024). "If the discordant results come from the difference in LOD between the tests, the tumors harboring the mutation would not be predominant in the whole tumor when the assumed tumor content was not overestimated, therefore poor EGFR-TKI efficacy is expected in these cases." (PMID 37612335, 2023). "Whether a tumor expresses EGFR or not could be used to stratify patients for anti-EGFR antibody therapies such as cetuximab, panitumumab, and nectitumumab." (PMID 37419997, 2023). "However, tumor-to-normal tissue contrast is confounded by intrinsic physiological limitations of heterogeneous EGFR expression and non-specific agent uptake." (PMID 36875185, 2023). "Anti-EGFR inhibitor-induced upregulation of MHC class I/II expression as well as the inactivation of GSK-3β/FoxP3 dampens Treg function and increases CTL activity is known as the main event that explains the modulation of the tumor immune microenvironment by cetuximab." (PMID 37143088, 2023). "For instance, anti-EGFR-LNPs loaded with Cas9 mRNA and PLK1 sgRNA enabled ~82% of PLK1 gene editing in human serous ovarian adenocarcinomas Ovcar8 (OV8) cells, which strongly inhibited tumor growth and increased overall survival by ~80% in metastatic OV8-bearing mice." (PMID 38516300, 2023). "Secondly, in non-operable NSCLC patients with no EGFR or ALK genomic tumor aberrations, first-generation PD-1/PD-L1 inhibitors, either as monotherapy or in combination with platinum-containing combination chemotherapy, has become the standard of care first line treatment." (PMID 36650586, 2023). "Heukers and colleagues performed co-culturing of high- and low- EGFR expressing tumor cells and adjusted the illumination and found that VHH-PS could be 100% specific to high EGFR expressing cells and safe for low EGFR expressing cells, which is in agreement with other studies." (PMID 37746282, 2023). "Further, the tumor cell surface expression of immune-activating (OX40L, CD137L, CD70, and ICOSL) and immune-suppressive (PD-L1, PD-L2, HVEM) checkpoint molecules and of an oncogenic molecule (EGFR) were measured via multicolor flow cytometry after CT and RT alone or after RCT." (PMID 36480032, 2023). "The data suggest that EGFR-HDAC axis mediates silencing of the chemokine gene cluster through chromatin conformational change, which might be relevant to the ICI resistance by creating T cell-deserted tumor microenvironment." (PMID 36991099, 2023). "In this autosomal dominant familial syndrome, inactivation of the FH tumor suppressor gene leads to the dysregulation of TCA cycle and the accumulation of HIF, resulting in the overexpression of proangiogenic growth factors, including VEGF and epidermal growth factor receptor (EGFR)." (PMID 37789902, 2023).
tumor (continued). "Thus, exosomes from EGFR-mutant adenocarcinoma sera may be potential mediators of mixed EMT and tumor invasion." (PMID 37122754, 2023). "Our observation is consistent with prior results demonstrating EGFR-YAP/TAZ signaling interplay during tumor progression, and further strengthens the fact that mechanical stimulation can drive changes in the EGF/EGFR signaling pathway impacting the oncogenic activity of TNBC." (PMID 36968199, 2023). "The 4-in-one CrossMab targeting EGFR, HER2, HER3 and VEGF 89 showed superior antitumor activity in different cancer models in vivo relative to combinations of BsAb, and they did so at lower antibody concentrations enabled by higher-avidity binding of tumor cells." (PMID 36793863, 2023). "Therefore, we hypothesized that TA on the ICG-Glow NPs efficiently binds to EGFR, CXCR4, FASN, and other oncoproteins, thus facilitating tumor specific binding/targeting which can further provide a novel option for tumor specific probe development." (PMID 37151801, 2023). "However, despite the initial response to EGFR kinase inhibitors, virtually all the EGFR-mutant patients eventually experience recurrence due to the sustained TKI-insensitive EGFR signaling in the TKI-treated tumors, leading to recurrent tumor resistance." (PMID 37178919, 2023). "Genetic deletion of HLA class I cell surface molecules augmented ADCP by anti-epithelial cell adhesion molecule (EpCAM) or anti-epidermal growth factor receptor (EGFR) antibodies, suggesting that the HLA class I:LILRB1 axis may compromise the therapeutic efficacy of tumor targeting antibodies." (PMID 37781391, 2023). "However, after treatment with trametinib, EGFR expression in tumor cells became independent of the proximity between tumor cells and host cells." (PMID 37501404, 2023). "This allows for tumor growth, although there is a lack of EGFR signaling." (PMID 36831661, 2023). "To verify YAP1 translocation and the upregulation of EGFR expression in preclinical models, we stained YAP1 and EGFR in tumor tissues of two patient‐derived xenografts (PDX), namely, PDX1 and PDX2, that were treated with trametinib in NSG mice and showed tumor growth delay." (PMID 37501404, 2023). "The observation that increasing tumor cell eccentricity generally leads to a higher likelihood of being predicted as non-benefitting from EGFR TKI Ttx suggests a connection between the elongated morphology of tumor nuclei and the epithelial-mesenchymal transition (EMT) process." (PMID 37461694, 2023). "The EMT process has been associated with EGFR TKI-resistant tumors, and thus, a higher tumor cell eccentricity in the non-benefitting group may indicate EMT activity, providing a possible explanation for the observed resistance." (PMID 37461694, 2023). "Preclinical models have also demonstrated that human epidermal growth factor receptor (EGFR) family inhibitors, SHP2 inhibitors, mammalian target of rapamycin (mTOR) inhibitors, and inhibition of CDK4/6 could enhance the anti-tumor activity of MRTX849 and inhibit KRAS-dependent signaling pathways." (PMID 37662925, 2023). "In HCC, the EGFR/PI3K/AKT/mTOR pathway is abnormally activated in approximately 50% of cases, and this dysregulated activation is involved in various cellular processes, including cell proliferation, tumor cell differentiation, autophagy, metabolism, and the epithelial–mesenchymal transition (EMT)." (PMID 37631344, 2023). "Apart from this, EGFR variant III (EGFRvIII), a tumor-specific deletion of exons 2-7 which occurs in approximately 30% of GBM patients, consistently activates the EGFR signal even without ligands binding, contributing to intra-tumoral heterogeneity and resistance to targeted therapies." (PMID 37601668, 2023). "Tumour heterogeneity may partly explain the reason why some tumours with wild-type KRAS status respond to anti-EGFR therapy while others do not." (PMID 37670299, 2023).
tumor (continued). "Moreover, in in vivo conditions, the proliferation of subcutaneously implanted A431 xenograft tumor cells lacking DUSP6 was more restricted compared to cells with normal expression of this phosphatase after the action of EGFR inhibitors." (PMID 37760412, 2023). "In contrast, in the vehicle‐treated mice, many tumor cells showed low or no expression of EGFR." (PMID 37501404, 2023). "In turn, tumours without EGFR amplification showed significantly lower ZEB1 expression." (PMID 37239035, 2023). "However, matched tumor-normal comparisons indicated that EGFR was not relatively upregulated in malignant tissues." (PMID 37251940, 2023). "Interestingly, data on the tumor cells’ evolution dynamics of EGFR-mutant NSCLC revealed that fusions do not commonly emerge as single alterations; rather, they frequently co-occur with additional on or off-target” mechanisms of resistance." (PMID 36765799, 2023). "It precisely expressed within tumor cells while a shared expression could hardly be found in normal tissues, such as EGFR vIII." (PMID 37046332, 2023). "Importantly, the cytotoxic activity of neutrophils driven by therapeutic EGFR or HER2 antibodies in vitro was increased by blocking the sialic acid/Siglec interaction, either by reducing tumor cell sialylation or by a Siglec-9 blocking antibody containing an effector silenced Fc domain." (PMID 37346044, 2023). "Since immunotherapy may be detrimental in the presence of EGFR mutations, TMB testing could be considered when the tumour is confirmed to be negative for EGFR and PD-L1." (PMID 36994206, 2023). "Furthermore, the oncogenic contexts were qualitatively different from each other: loss of tumor suppressors generally led to increased rates of tumor initiation and growth in the KRAS backgrounds, had more muted effects in the BRAF context, and had variable effects in the EGFR context." (PMID 37828026, 2023). "The first generation of anti-cancer mAbs were those which target the tumour cells directly by binding to surface antigens, including rituximab (anti-CD20), trastuzumab (anti-human epidermal growth factor receptor-2; HER-2) and cetuximab (anti-epidermal growth factor receptor; EGFR)." (PMID 37652365, 2023). "Both screens identified ALK as the most effective combination target, altogether demonstrating that partial sensitivity to ALKi primary tumor cells was regulated by EGFR and PI3Kβ and could be effectively overcome by combined inhibition of ALK and EGFR or PI3Kβ." (PMID 36423211, 2023). "Upon binding of EGF or other ligands, EGFR is activated and induces the activation of downstream signaling pathways, including Ras-MAPK, PI3K/Akt, JAK/STAT, and PLCγ/PKC pathways, which leads to tumor cell proliferation, angiogenesis, tumor invasion, metastasis, and inhibition of apoptosis." (PMID 37974093, 2023). "The knockdown of NANOG in the cisplatin-resistant tumor cells led to a significant decrease in autophagosome abundance, EGF secretion and the level of pEGFR, suggesting an important role of NANOG in regulating the autophagy-mediated EGFR activation of cisplatin-resistant tumor cells." (PMID 37165076, 2023). "Targeting wild-type EGFR could not solve the issue completely as the expression of wild-type EGFR is not restricted to tumor cells only, thus triggering the likelihood of off-target toxicity." (PMID 36721153, 2023). "Similarly, considerable reduce of MDA-MB-231 cells-derived tumor nodules in lung were also detected in mice with both PELI1 knockdown and EGFR inhibition, as further confirmed by the decreased GFP fluorescence intensity indicating the MDA-MB-231 cells number in lung." (PMID 36841821, 2023). "In addition to tumor stage and size, this model also included demographic factors (age, menopausal status, race, smoking, BMI), Basal marker expression (CK5/6 or EGFR), detection method (screening vs. self-detected), and treatment (chemotherapy, radiation therapy, and targeted therapy)." (PMID 37293118, 2023).
tumor (continued). "This probe could therefore be used to determine EGFR expression levels in vivo, overcoming limitations of punch biopsies, which due to their small size do not represent the whole tumor." (PMID 37419997, 2023). "Based on the anti-tumor activity and favorable toxicity profile of DS-1205c in nonclinical models, the use of DS-1205c in combination with an EGFR TKI was investigated in patients with metastatic or unresectable EGFR-mutant (T790M-negative) NSCLC in a multicenter, open-label, phase 1 Japanese study." (PMID 36892745, 2023). "Similarly, overexpression of EGFR H score was significantly observed in non-tumorous liver tissue and tumour groups (p = 0.007 and p < 0.001, respectively)." (PMID 38414954, 2023). "Patients with EGFR-mutant advanced disease with MRD negative status after local treatment or tumor burden on imaging may undergo an EGFR-TKI “drug holiday”." (PMID 37069698, 2023). "Because PRV oncolytic agents can stimulate specific antitumor immunity, they effectively inhibit tumor recurrence and metastasis, which may not be restored by small-molecule EGFR inhibitors." (PMID 37891570, 2023). "In addition to ZEB-related double negative feedback loop and EGFR amplification status, there are also many other epigenetic mechanisms that can affect miR-200s in tumour progression." (PMID 37239035, 2023). "Therefore, the combined blockade of EGFR and type I IFN signalling could enhance the efficiency of EGFR inhibitors in vitro and result in reduced tumour cell growth in vivo." (PMID 37483492, 2023). "Similarly, to the dysfunction of EGFR signaling, amplification of the Met proto-oncogene (MET) and overexpression of the tyrosine protein kinase Met (c-Met) also play a significant role in tumor development and treatment resistance." (PMID 37373500, 2023). "Also, TAMs are key players in the antitumor activity of selected monoclonal antibodies (mAbs) such as rituximab (anti-CD20), trastuzumab (anti-HER2), cetuximab (anti-EGFR), and daratumumab (anti-CD38), as they express FcγR to perform tumor-cell killing and phagocytosis." (PMID 38033495, 2023). "Indeed, the effects of tumor suppressor inactivation on growth across oncogenic KRAS-, BRAF-, and EGFR-driven tumors were uncorrelated (Spearman ρ = 0.41 for BRAF versus G12C, ρ = 0.14 for EGFR versus G12C)." (PMID 37828026, 2023). "In addition, the antibody enhanced ADCP by the anti-EGFR antibody cetuximab in vitro, thereby providing further evidence that LILRB1 blockade may enhance the therapeutic efficacy of tumor targeting antibodies by enhancing their ADCP function." (PMID 37781391, 2023). "Twenty-four transcripts were downregulated in recurrence among EGFR non-amplified tumours, and among these was TARDBP (padj = 0.034), coding for the neuronal protein TDP-43, involved in the transcriptional response in neurodegenerative disease via widespread RNA binding interactions." (PMID 36765632, 2023). "However, panitumumab, the fully human IgG2 antibody anti-EGFR, has not demonstrated the same skills in mobilizing immune cells against tumor cells." (PMID 36765821, 2023). "Also, in other tumour types, such as NSCLC, EGFR genotyping through ctDNA assessment is well-accepted, especially when invasive procedures may be risky or contraindicated." (PMID 37509239, 2023). "Izumchenko and colleagues showed that silencing of tumor suppressor miR-200 could upregulate the expression of negative EGFR regulator of mitogen-inducible gene 6 (MIG6) in the process of transforming growth factor β (TGFβ)-mediated EMT." (PMID 37560164, 2023).
tumor (continued). "In addition, it has also been shown that tumor-derived EVs may enhance the radiosensitivity of NPC by delivering miR-142-5p to radiotherapy-resistant NPC cells to inhibit the HGF/c-Met and EGF/EGFR pathways." (PMID 36968209, 2023). "Another study elucidated the way in which antagonistic anti-EGFR nanobodies that were selected using the phage display technology effectively blocked the binding of endothelial growth factor (EGF) to EGFR and EGF-mediated signaling and delayed tumor outgrowth in vivo." (PMID 37243023, 2023). "A pragmatic example is the patient with early-stage disease who may be a candidate for neoadjuvant chemoimmunotherapy, provided the tumor does not harbor EGFR or ALK alterations." (PMID 36980426, 2023). "Interestingly, selective HER2 YVMA inhibition was shown, which suffices to suppress tumor growth, as inhibition of wild-type EGFR did not appear to confer a meaningful therapeutic effect." (PMID 36831628, 2023). "The reactivity to the EGFR peptides was highly specific to this mutant EGFR, which indicated by the lack of response present in non-vaccinated but tumor-bearing animals, suggesting that the immune responses were induced by vaccination but not the boosting effect promoted by tumor inoculation." (PMID 36875137, 2023). "On the other hand, it has been also demonstrated that in several tumor cell lines (SCC, colon, and lung), EGFR phosphorylation induces mPGES-1 upregulation through the activation of ERK1/2 and Egr-1 signaling, and that this enzyme drives the protumoral activity of EGFR." (PMID 37190301, 2023). "In particular, KRASG13D but not KRASG12V tumours were shown to be sensitive to EGFR inhibition." (PMID 37627169, 2023). "Activated EGFR signaling can also recruit or reprogram suppressive immunocytes, inhibit major histocompatibility complex (MHC) molecule levels, and upregulate inhibitory cytokines and metabolites, which induces the immunosuppressive tumor microenvironment (TME)." (PMID 36812484, 2023). "By co-modified with the CD133 + ligand (A15) and EGFR aptamer (CL4), CECP NPs achieved dual targeting effects of OSCs and OS cells, which reduced fourfold tumor spheres formation and the percentage of CD133 + cells, and obtained a 90% decrease of tumor volume in vivo." (PMID 36944946, 2023). "Administration of anti-CD73 regent increases tumor cell death in vitro, and CD73 blockade exhibits slower tumor outgrowth and significantly increased antigen-specific CD8+ T-cell immunogenicity following treatment with pemetrexed in an EGFR-mutant lung cancer mouse model." (PMID 36982618, 2023). "For the large group of RAS mutated tumours, chemotherapy is often combined with anti‐VEGFR antibodies, but this combination‐treatment could not reach the same OS rates as anti‐EGFR‐targeted therapy in clinical trials." (PMID 37604687, 2023). "In our cohort, MEOX2 immunoreactivity was significantly higher in the subset of EGFR-amplified GBMs (96.7%, 29/30); it was commonly seen in the rest of the GBMs (70.2%, 33/47) and only rarely observed in IDH1mt tumours (5.9%, 2/34) and non-diffuse gliomas (4.3%, 1/23)." (PMID 37568909, 2023). "Interestingly, EGFR signaling in cancer pathways was not enriched with either tumor-tumor interaction or tumor-stroma interaction, consistent with previous observations showing that EGFR expression is not predictive of EGFR TKI response." (PMID 36647832, 2023). "Interestingly, increasing tumor cell eccentricity generally raised the likelihood of being predicted as non-benefitting from EGFR TKI Ttx." (PMID 37461694, 2023).